CHEK2 (checkpoint kinase 2)
Diseases named in the same sentence as CHEK2 in open-access papers (continued):
Sharing a sentence is not in itself a finding about the gene and the disease.
tumor (continued). "In the Netherlands, observed putative PGVs in dominant genes that do not match the tumor type (ATR, CHEK2 (3x), SDHA and MITF) are normally not reported back to the patient, except if there is a matching personal and/or familial history." (PMID 41168197, 2025). "CHEK2 in GBM continuously activates the cell cycle checkpoint, allowing tumor cells to enter the cell cycle without DNA damage repair, increasing genomic instability." (PMID 41497799, 2025). "We also observed a shorter BCSS in CHEK2 c.1100delC carriers compared to non-carriers, after accounting for CBC occurrence, age at diagnosis of the first primary BC and tumor characteristics." (PMID 36824750, 2023).
infection (35 papers, 2009 to 2025). The state of being infected such as from the introduction of a foreign agent such as serum, vaccine, antigenic substance or organism. "Crucially, this restored CHEK2 expression correlated with its subcellular redistribution—shifting from nuclear retention following infection to mitochondrial translocation upon kinase inhibition." (PMID 40437411, 2025). "We confirmed that S. aureus infection suppressed Chek2 mRNA expression in BMDMs as early as 4 h post-infection." (PMID 39102432, 2024). "After 9 h of infection, an upregulation of TLR3 mRNA was observed compared to control, while the CHEK2 mRNA could not be detected in THP-1 cells exposed to WN stool sample." (PMID 35732858, 2022).
hematologic cancers (3 papers, 2007 to 2025). "Reports of increased risk of lymphoid and hematologic malignant neoplasms (especially CLL) in individuals with heterozygous CHEK2 variants date from 200621,31,32 but were conflicting and/or based on highly ascertained families." (PMID 41396600, 2025).
hematologic disease (3 papers, 2022 to 2025). "We identified six individuals with solid tumors or hematologic disease with germline CHEK2 alterations at Nationwide Children’s Hospital between 1 December 2017 and 1 November 2022." (PMID 36980535, 2023). "In addition to the genes known to predispose to hematological malignancies, patients harbored several interesting variants in genes primarily associated with an increased risk for solid tumors (MUTYH, PMS2, and CHEK2)." (PMID 35739278, 2022).
autosomal dominant disease (2 papers, 2011 to 2018). Autosomal dominant form of disease.
blood cancers (2 papers, 2022 to 2025).
CNS tumors (2 papers, 2022 to 2023). "In consideration of the unavailability of family patient samples, the relationship between CHEK2 mutations and CNS tumors needs more research and reports in the future." (PMID 35281821, 2022). "In the future, olaparib combined with temozolomide/radiotherapy might be a promising treatment option for patients with CNS tumors harboring the CHEK2 germline mutation." (PMID 35281821, 2022). "Currently, there is no direct evidence supporting the relationship of CHEK2 with central nervous system tumors." (PMID 35281821, 2022). "Currently, there is no direct evidence supporting the relationship of CHEK2 with CNS tumors." (PMID 35281821, 2022).
neurological disorders (2 papers, 2024 to 2025). "Specifically, we identified sexually dimorphic features in the adult zebrafish brain that depend on microglia and Chek2, which may have broader implications and represent therapeutic targets for sex-biased neurological disorders." (PMID 40894757, 2025).
CHEK2 also shares sentences with these, for which no sentence is quoted: nasopharyngeal carcinoma (8 papers); virus infection (6); adenocarcinoma (5); Breast (5); esophageal squamous cell carcinoma (5); familial prostate cancer (5); hereditary breast and ovarian cancer (5); stomach cancer (5); Cowden syndrome (4); diffuse large B-cell lymphoma (4); esophageal cancer (4); Familial adenomatous polyposis (4); chordoma (3); cyst (3); head and neck squamous cell carcinoma (3); lung squamous cell carcinoma (3); neurodegenerative disease (3); paraganglioma (3); rhabdomyosarcoma (3); serous carcinoma (3); uterine cancer (3); B-acute lymphoblastic leukemia (2); Burkitt lymphoma (2); coronary artery disease (2); Crohn disease (2); developmental delay (2); digestive-system tumors (2); endocrine glands tumors (2); fibrosarcoma (2); gallbladder carcinoma (2).
A further 140 diseases each share a sentence with CHEK2 in 2 papers or fewer.